CD4 (CD4 molecule)
Diseases named in the same sentence as CD4 in open-access papers (continued):
Sharing a sentence is not in itself a finding about the gene and the disease.
Sepsis (continued). "In murine models of sepsis, CTLA4 was also reported to be elevated on CD4+ and CD8+ T cells." (PMID 28363639, 2017). "Although the size of the spleen from T. gondii-infected mice was similar to naïve mice, after the induction of sepsis, T. gondii-infected mice experienced a notable reduction in spleen size along with a striking emergence of IFN-γ- and TNF-α-producing CD4+ and CD8+ T cells into the peritoneum." (PMID 28439500, 2017). "Thus, the presence of long-lived T. gondii-experienced CD4+ and CD8+ T cells was more influential in aggravating sepsis than bacterial translocation." (PMID 28439500, 2017). "In our study, we used T cell–specific Atg5 knockout mice (CD4-Cre recombinase/Atg5f/f mice: CD4-Cre/Atg5f/f mice) and performed a CLP procedure to prove our hypothesis that autophagy is related to apoptosis in sepsis." (PMID 27618275, 2017). "Twenty-four hours after sepsis, there was a significant increase in the frequency of CD69+ CD43+ cells within the CD4+CD44hi subset in water sepsis but not alcohol sepsis." (PMID 27861506, 2016). "In summary, this is indicative of two opposing mechanisms of negative immune cell activation feedback in CD4+ cells in patients who have survived sepsis." (PMID 27056672, 2016). "Taken together, these data suggest that the reduced CD43 and CD69 expression observed on CD4+ and CD8+ T cells in ethanol-fed animals in the setting of sepsis may be responsible for the dysregulated cytokine response." (PMID 27861506, 2016). "Within 24h, there was a significant increase in the frequency of CD69+CD43+ cells within the CD44lo CD4+ T cell population in water sepsis, while the increase in alcohol sepsis failed to reach significance." (PMID 27861506, 2016). "At 72 hours, there were no significant changes in CD4+ frequency due to the additional of alcohol alone or in synergy with sepsis as seen by comparison of the H2O CLP and EtOH CLP groups." (PMID 27861506, 2016). "At present, proliferation and apoptosis of CD4+ T lymphocytes and the relationship between them were not systematically elaborated in the setting of sepsis." (PMID 26577833, 2015). "Then, we analyzed the association between PD-1/PD-L1 expression and patient prognosis by comparing expression levels of PD-1 and PD-LI on CD4+ T cells and monocytes obtained from sepsis survivors and nonsurvivors." (PMID 26063974, 2015). "We observed that CD4+ T cell count, CD8+ T cell count, B cell count, and antibody count were persistently elevated, which contributed to the pathogen clearance during a late stage of sepsis progression." (PMID 26446682, 2015). "A study by Shubin and colleagues showed that increased BTLA+CD4+ lymphocytes were found in patients who developed a subsequent infection, and that BTLA may be a potential biomarker and mediator of sepsis-induced immunosuppression." (PMID 26329820, 2015). "Reconstitution with CD4+ or double-negative subsets or with iNKT cells isolated from different tissues will enable functional studies on these cells in the context of sepsis." (PMID 26322041, 2015). "CD4+ T and CD8+ T cells mediate the host response to sepsis in various ways." (PMID 26446682, 2015). "Interestingly, several months after recovery, survivors who received hydrocortisone treatment during sepsis in our study still had reduced numbers of CD3+ and CD4+ T lymphocytes and B lymphocytes well after recovery." (PMID 26215823, 2015). "Additionally, there is a subclass of CD4 + CD25+ T lymphocytes, known as TReg cells that are upregulated in sepsis." (PMID 25887317, 2015). "• Aging decreased the proportion of naive T cells and increased that of memory CD4+ T cells with high expression of negative co-stimulatory molecules in patients and mice with or without sepsis." (PMID 24962182, 2014).
Sepsis (continued). "In addition to an increase in the percentage of circulating CD3+CD4+CD25+ Treg cells in the peripheral blood, we further demonstrated the restoration of Treg cell suppressive function in rats with sepsis after MSC administration." (PMID 25337817, 2014). "In sum, we concluded from these results that an episode of SIRS or sepsis did not compromise the intrinsic ability of CD4+ and CD8+ effector T-cells to respond to cognate antigens on a per cell basis." (PMID 25541945, 2014). "Animals from the various SIRS/sepsis groups featured fluctuations, albeit not significant, in numbers of Ag-specific IFNγ+ CD4+ T-cells, probably reflecting the individually distinct early loss of relevant naive T-cell precursors (data not shown)." (PMID 25541945, 2014). "Our data showed that CD4 count had no influence on either the incidence (p = 0.57) or severity (p = 0.21) of pin track sepsis in the HIV-positive group." (PMID 25056512, 2014). "Compared with non-survivors with severe sepsis, survivors had higher Treg, Th1, Th17 and total CD4+ lymphocyte counts in this work." (PMID 23670410, 2013). "Additionally, other studies have found that BTLA contributes to CD4+ T-cell apoptosis in mice; we therefore assessed the contribution of BTLA in lymphocyte apoptosis in our model of sepsis." (PMID 24289156, 2013). "Since HIV-1 subtype affects the rate of CD4-cell decline and HIV viral load changes, it would therefore affect how early and how often an individual may develop sepsis." (PMID 23144755, 2012). "Time to first development of sepsis or frequency of septic episodes may be related to length of HIV seropositivity, rate of CD4 decline, HIV viral load rise and HAART use." (PMID 23144755, 2012). "Patients with clinical signs of sepsis had lower CD4+ counts compared to patients without sepsis (P < 0.001)." (PMID 21658212, 2011). "The sepsis classification system that is currently used is not representative of the individual immune status as determined by measuring the CD4+ lymphocyte ATP content." (PMID 20540723, 2010). "Among patients with CAP or intraabdominal infections and severe sepsis/shock, absolute counts of CD4-lymphocytes were significantly decreased compared with patients with CAP or intraabdominal infections and sepsis (P of comparisons 0.024 and 0.027 after adjustment for multiple comparisons)." (PMID 20504311, 2010). "Regarding adaptive immunity, absolute counts of CD4-lymphocytes were significantly decreased among patients with severe sepsis/shock due to community-acquired pneumonia (CAP) and intraabdominal infections compared with sepsis." (PMID 20504311, 2010). "In summary, we have demonstrated that the sepsis classification system that is currently used does not accurately reflect the immune status of an individual when measured by determining the CD4+ lymphocyte ATP content." (PMID 20540723, 2010). "Notably, CD3% and CD4% exhibited a negative correlation with the APACHE II scores in sepsis patients (r = -0.214, p = 0.0103; r = -0.237, p = 0.0043), while CD3% showed a negative correlation with the SOFA score (r = -0.242, p = 0.0287)." (PMID 40642098, 2025). "To further explore whether DOCK2 regulates IFN-γ–producing CD4+ T cells that trigger LPS-induced sepsis or not, firstly, we detected the role of IFN-γ in DOCK2-deficient mice when they suffered from endotoxin-induced septic shock." (PMID 40510337, 2025). "However, in sepsis patients with drug-resistant bacterial infections, PD-1 levels are increased in CD4+ and CD8+ T cells compared to critically ill non-septic patients." (PMID 41158471, 2025). "Combining the identified top 20 differentially expressed proteins and KEGG pathway enrichment analysis, it was inferred that the cGAS-STING signaling pathway might play a potential role in CD4+ T lymphocyte PANoptosis, regulated by NUFIP1-mediated ribophagy in sepsis." (PMID 40995563, 2025).
Sepsis (continued). "In this context, the profound CD4+ T-cell lymphocytopenia likely stemmed from the combined insults of disseminated TB, HLH, and septic shock, mediated by mechanisms including activation-induced cell death, hyperinflammatory cytotoxicity, and sepsis-induced immunoparalysis." (PMID 41357205, 2025). "In addition, CD4+ T lymphocytes were isolated from peripheral blood samples in sepsis and nonsepsis patients, validating the significance of ribophagy and PANoptosis in clinical cases." (PMID 40995563, 2025). "Indeed, flow cytometry indicated higher relative abundance of PD-1+CD4+ Tm cells and CD69+CD4+ Tm cells in patients with heatstroke than in healthy control and patients with cardiopulmonary bypass, but not in patients with sepsis." (PMID 40084252, 2025). "However, abnormal autophagy states may be detrimental; for instance, blocking autophagy in CD4+ T cells increases IL-10 secretion, which inhibits differentiation of IFN-γ-producing Th1 cells and natural killer (NK) cell activation in sepsis." (PMID 40817040, 2025). "Furthermore, we compared the expression intensity of biomarkers on CD4+ T lymphocytes between survivors and non-survivors based on 28-day mortality of all the patients with sepsis." (PMID 39104530, 2024). "The literature describing the role of CD4+ TFR cells in sepsis is sparse, however, could provide important insight into functional changes to CD4+ TFH cells if severe bacterial infections drive a similar expansion of CD4+ TFR cells as seen in HIV infection." (PMID 38197178, 2024). "We found that neither the frequency nor the number of basophils producing IL4 in the spleen and liver were increased, implying that IL4-producing immune cells such as CD4+ T cells and basophils are not essential for mediating the protective effects of α-GalCer pretreatment against sepsis." (PMID 39355237, 2024). "Decline of helper T cell populations during sepsis creates an environment in which CD8+ T cells could proceed to respond to antigen without CD4+ T cell help." (PMID 38197178, 2024). "Furthermore, Spearman’s correlation analysis revealed that MASP-1 expression was significantly negatively correlated with naive B cells, naive CD4 T cells, and CD8 T cells and significantly positively correlated with M0 macrophages, monocytes, and neutrophils in trauma and sepsis." (PMID 38384415, 2024). "Measurement of CTLA-4 expression in the CD4+Foxp3− Tconv (CD4+ Tconv), CD4+Foxp3+ Treg (CD4+ Treg), and CD8+ T cell compartments of these mice after alcohol exposure and tamoxifen administration followed by CLP verified decreased CTLA-4 expression on both CD4+ Tconv and CD4+ Treg during sepsis." (PMID 38226924, 2024). "Some animal studies have shown that CD4+ T cells may directly mediate the host response to sepsis, while others have shown that they had no impact on the inflammatory response." (PMID 39290582, 2024). "We first observed that circulating Treg frequencies (CD3+CD4+CD25+CD127-FOXP3+) and expression of Foxp3 in CD3+CD4+CD25+CD127- cells were significantly increased in patients with prenatal risk factors but were not seen if associated with clinical sepsis." (PMID 39072327, 2024). "In addition, the percentage of CD4+ cells expressing CTLA-4 and CTLA-4 MFI on CD4+ cells were also higher among non-surviving patients with sepsis (90.2% versus 50.3%, P<0.0001; and 427.5 versus 130.6, P=0.002, respectively)." (PMID 39104530, 2024). "The MFI of CTLA-4, LC3II, mTOR, and P62 on CD4+ cells were significantly higher in patients with sepsis than in non-septic patients (185.5 versus 104.4, P<0.0001; 152.3 versus 99.6, P=0.001; 166.8 versus 143.6, P=0.029; and 244.0 versus 177.2, P=0.001, respectively)." (PMID 39104530, 2024).
Sepsis (continued). "And the percentage of suppressor T lymphocyte and natural killer cell in severe sepsis group were significantly higher than those in non-severe group, while the CD4+/CD8+ T lymphocyte ratio was significantly lower in KD with severe sepsis group than in KD with non-severe sepsis group." (PMID 37234775, 2023). "To test whether changes in splicing occur in immune-related conditions, we used the GSE60424 dataset, which includes six cell types (B, CD4, CD8, NK, neutrophils, and monocytes) from healthy donors and donors with different pathological conditions, namely, ALS, type 1 diabetes, MS or sepsis." (PMID 37711610, 2023). "Conversely, Activated CD8 T cell, Central memory CD4 T cell, Effector memory CD8 T cell, Eosinophil, MDSC, Monocyte, Natural killer T cell, Neutrophil, T follicular helper cell, and Type 1 T helper cell showed more significant expression in sepsis cluster 2 (P<0.05)." (PMID 38332910, 2023). "Moreover, EVs from patients with sepsis-induced lung injury and LPS-treated CD4+ T cells further increased the levels of ALT, AST, and LDH in CLP mice compared with EVs from control subjects and from untreated CD4+ T cells." (PMID 36959535, 2023). "We show further that the direct contact between CD4 molecule of CD4+ T cells or the ectodomain of CD4 (soluble CD4, sCD4), and MHC II of resident macrophages is necessary and sufficient to prevent TLR4 overactivation in LPS and cecal ligation puncture (CLP) sepsis." (PMID 37332010, 2023). "Moreover, we found that S100A9+ monocytes exhibited profound immunosuppressive function on CD4+ T cell immune response and blockade of S100A9 using Paquinimod could partially reverse sepsis-induced immunosuppression." (PMID 37337301, 2023). "In this study, five downregulated lncRNAs in sepsis groups, including LINC00861, LINC01278, RP11−156P1.3, RP11−264B17.3, and RP11−284N8.3, were positively correlated with several immune cells, including CD8+ T cells, CD4+ memory T cells, Tregs, NK cells, and resting dendritic cells." (PMID 36817490, 2023). "The level of CD4 and CD8 expression, calculated as the mean of fluorescent intensity, decreased after 120 days of infection in CD4+ T and CD8+ T cells, respectively, in comparison with 24 hours after sepsis development (P<0,001***) while CD4 and CD8 expression was higher in healthy controls." (PMID 38094297, 2023). "In addition, multiple clinical studies show that amplification of CD4+CD25+ Tregs and increased Foxp3 levels may increase risks of nosocomial infections or secondary infections in sepsis." (PMID 35281010, 2022). "Second, CMV‐specific CD8+ and CD4+ T cells were not selected for subpopulation analysis because the purpose of this study was to explore the role of host immune phenotype in CMV‐infected patients with sepsis." (PMID 36106958, 2022). "To determine whether the sex-specific effects of purinergic signaling blockage that we noted in mice during sepsis is also observed in human cells, we investigated whether blocking P2Y1 or P2Y12 signaling pathways influence CD4 and CD8 differentiation when PBMCs cells are stimulated with LPS." (PMID 36405709, 2022). "Moreover, we observed that the prevalence of vitamin D insufficiency in neonates with infectious pneumonia, sepsis, cytomegalovirus infection, and hypocalcemia was higher and the serum CD3+, CD3+, CD4+, and IgA levels were lower in neonates with vitamin D insufficiency." (PMID 35722480, 2022). "Diminished pro-inflammatory responses upon re-stimulation of blood leukocytes may relate to a reduced capacity to activate nuclear factor-κB, as pointed out by intracellular flow cytometry of ex vivo stimulated monocytes, CD4+ T cells, CD8+ T cells, B cells and neutrophils from patients with sepsis." (PMID 36470832, 2022).
Sepsis (continued). "The ratio of CD3+CD4+CD69+T/CD3+CD8+CD69+T (odds ratio (OR): 0.078(0.012,0.506), P = 0.008), PCT>0.53 ng/ml (OR: 9.31(1.36,63.58), P = 0.023), and CO2CP<26.5 mmol/l (OR: 10.99(1.29, 93.36), P = 0.028) were predictive of G- sepsis (versus G+ sepsis), and the area under the curve (AUC) was 0.947." (PMID 36703970, 2022). "We have also shown that in DC patients with sepsis, MDSCs significantly enhanced the expression of FOXP3 on CD4+ T cells and behaved as Tregs, while stimulation with l-NMMA (iNOS inhibitor) and nor-NOHA (inhibitor of Arginase1) significantly suppresses the expansion of Tregs in sepsis patients." (PMID 35720398, 2022). "From a therapeutic perspective, the cell death of CD4 lymphocytes may not be modulated by TLR4 inhibition in patients with sepsis." (PMID 34733114, 2021). "In the CLP-induced sepsis model, EA at ST36 decreased the circulating d-lactose in serum, which means intestinal permeability, and increased IgA level, percentage of CD3+, γ/δ, CD4+, CD8+ T lymphocytes, and the ratio of CD4+/CD8+ T cells in intestinal mucosa cells." (PMID 35095910, 2021). "However, because there were high numbers of activated CD4+ T cells when the T-cell compartment had recovered after sepsis, other non-HP mechanisms have been suggested to explain CD4+ T-cell recovery." (PMID 32825352, 2020). "Additionally, no skewing in TCR Vβ expression in memory CD4 T cells following sepsis was observed, suggesting numerical recovery was not due to Ag-driven proliferation of cells responding to infection during sepsis." (PMID 32733454, 2020). "Sepsis reduces the number of MOG-specific CD4 T cells but not their capacity to proliferate." (PMID 33191915, 2020). "With these tools, we established that sepsis diminishes the number of MOG-specific CD4 T cell precursors but does not alter capacity of the surviving cells to proliferate (either by intrinsic or extrinsic mechanisms) or promote disease if numerically bolstered." (PMID 33191915, 2020). "Ag-driven proliferation also is likely to play a role for some Ag-specific CD4 T cell populations, as CD4 T cells recognizing epitopes derived from gut-derived segmented filamentous bacterium (SFB) were found to proliferate in an Ag-dependent manner following sepsis." (PMID 32733454, 2020). "However, most (if not all) of the previous studies examined the effect of sepsis on the CD4 T cell compartment in sum, which has the potential to mask some of the unique characteristics of individual Ag-specific populations." (PMID 32903436, 2020). "In contrast, antibody is necessary for prevention of sepsis but CD4+ cellular responses are not." (PMID 30881363, 2019). "In the current study, we carried-out an ex vivo experiment to assess CD4 T cell proliferation; in parallel we also assessed the expression of apoptosis inducing proteins in spleen at multiple time points after CLP in order to better understand about these two events in sepsis." (PMID 30052667, 2018). "Since the expression of apoptosis inducing proteins did not alter at day 2 and 3 of sepsis, the prolonged decreased levels of CD4 T cells in the spleen could be due to their proliferation defect." (PMID 30052667, 2018). "In context of sepsis, the role of ghrelin on CD4 T cell proliferation was not clearly known." (PMID 30052667, 2018). "Thus, the accumulation of CD4+ DCs in the bone marrow during sepsis is regulated by CCR2 but seems to be independent of monocyte mobilization." (PMID 29218051, 2017). "Thus, T. gondii-programmed CD4+ and CD8+ T cells may be recruited to the site of sepsis and are the primary source of inflammatory mediators during sepsis in infected mice." (PMID 28439500, 2017). "Compared with sham group, CD3+, γ/δ, CD4+, and CD4+/CD8+ T lymphocytes were significantly decreased from (80.75 ± 10.24)%, (18.64 ± 7.73)%, (24.59 ± 6.60)%, and (1.89 ± 0.52) to (38.38 ± 10.90)%, (7.62 ± 1.79)%, (7.95 ± 2.95)%, and (0.97 ± 0.67) in the sepsis group." (PMID 26346309, 2015).